FGF23 (fibroblast growth factor 23)
Diseases named in the same sentence as FGF23 in open-access papers (continued):
Sharing a sentence is not in itself a finding about the gene and the disease.
hyperphosphatemia (continued). "In fact, CKD alters hormonal processes that regulate phosphate levels (intestinal absorption, renal excretion by remaining nephrons, bone metabolism modulated by vitamin D, fetuin-A, Klotho, and fibroblast growth factor 23 (FGF-23); all these processes mentioned favoring hyperphosphatemia." (PMID 37510208, 2023). "Even though elevated plasma Pi is considered a driver for secondary hyperparathyroidism and elevated plasma FGF23 levels, hyperphosphatemia does not occur until later stages in CKD." (PMID 34994388, 2022). "The absence of FGF23 or Klotho leads to hyperphosphatemia and resulting premature aging features in mice." (PMID 35928251, 2022). "Hyperphosphatemia promotes and triggers the progression of vascular calcification by inducing VSMC apoptosis, leading to the transdifferentiation of VSMCs to osteoblasts, elevating FGF23 levels, and decreasing Klotho expression." (PMID 35080671, 2022). "Thereafter, neither PTH or FGF-23 are capable of completely maintaining phosphate balance and hyperphosphatemia ensues." (PMID 36615824, 2022). "In those cell types, FGF23 expression is stimulated by the calcitriol (via the vitamin D receptor [VDR] signaling pathway) and hyperphosphatemia (via the sensing of extracellular phosphate levels mediated by type III sodium-dependent phosphate transporter [PiT2]) and FGFR1c." (PMID 35269640, 2022). "Lack of Klotho or FGF23 results in hyperphosphatemia and hypervitaminosis D. With age, human renal function often deteriorates, lowering Klotho levels." (PMID 35903083, 2022). "Hardcastle and Dittmer (2015) postulate that FGF23 reacts on acute rather than on long-term hyperphosphatemia." (PMID 33606750, 2021). "In addition, it has been shown that FGF23, in an αKlotho-dependent manner, suppresses PTH secretion, which is reduced in CKD and that the CaSR suppressive effect is also reduced because of hyperphosphatemia-related decreased expression of the CaSR." (PMID 33416083, 2021). "Taken together, the effect of phosphate binders on FGF23 levels cannot be expected in pre-dialysis CKD patients without hyperphosphatemia, and thus a dietary therapy-based strategy was recommended." (PMID 34069053, 2021). "Our study investigated the clinical relevance of increased FGF‐23 concentrations in dogs with CKD but without hyperphosphatemia." (PMID 34418162, 2021). "In comparative in vivo studies, LVH was only present in mice with high intra-cardiac Fgf23 synthesis and hyperphosphatemia and not in those with normal serum phosphate concentrations." (PMID 34778257, 2021). "Populational studies have pointed out that, in CKD patients, the increase in FGF-23 and PTH, accompanied by the decrease in 1,25 dihydroxyvitamin D3, anticipate hyperphosphatemia, which is often observed in these patients and is usually related to a higher mortality risk among them." (PMID 35056905, 2021). "Conversely, other mutations in FGF23 which result in an increase in FGF23 processing and subsequent decrease in circulating intact FGF23 levels lead to familial tumoral calcinosis (FTC), a human disease characterized by hyperphosphatemia and heterotopic calcification." (PMID 34149625, 2021). "MBDs include changes in serum calcium (Ca2+) concentration, increased serum phosphate levels (hyperphosphatemia), reduced serum levels of active vitamin D, secondary increase of parathyroid hormone (PTH), augmented FGF-23 systemic levels, and reduced levels of the antiaging factor Klotho." (PMID 34867481, 2021). "It has been observed that in the early stages of CKD when hyperphosphatemia and hyperparathyroidism have not yet developed, there are elevated levels of FGF-23." (PMID 32823917, 2020). "Compared with Klotho+/+ (WT) mice, KLKO mice exhibited high plasma concentrations of FGF23 and 1,25(OH)2D3, hyperphosphatemia, and hypercalciuria, but not ionized Ca or PTH." (PMID 32026654, 2020).
hyperphosphatemia (continued). "Although the FGF23 antibody treatment normalized levels of calcium, calcitriol, PTH and bone markers, the rats had increased mortality due to cardiovascular events related to hyperphosphatemia." (PMID 33233840, 2020). "The present study also showed that despite an increase in the FGF23 serum level in the studied thalassemia patients affected by hypoparathyroidism and hyperphosphatemia, no rise in the urinary phosphate excretion was observed." (PMID 33198660, 2020). "In ESRD, FGF23 fails to sustain phosphate homeostasis and hyperphosphatemia and increased FGF23 levels stimulate the development of hypertension, vascular calcification, and left ventricular hypertrophy." (PMID 32635646, 2020). "A global genetic deletion of FGF23 in mice resulted in severe hyperphosphatemia, due to the absence of the FGF23-mediated phosphaturia mechanism." (PMID 32982979, 2020). "This indicates that DMP1 specifically inhibits FGF23 production and that the inhibitory effects of DMP1 may supersede any direct stimulatory effects of hyperphosphatemia." (PMID 31044094, 2019). "This leads to a further compensatory increase in FGF-23 levels which fails to exert its phosphaturic and PTH-suppressing effects without Klotho, thereby enhancing hyperphosphatemia and overt hyperparathyroidism, conditions at high risk for CVD." (PMID 30200452, 2018). "As would be expected since FGF23 regulates phosphate excretion, FGF23 levels increase as renal function declines, resulting in elevated circulating levels of FGF23 in CKD, albeit with hyperphosphatemia due to reduced GFR." (PMID 30155452, 2018). "Low calcium and hyperphosphatemia further exacerbate SHPT and elevate PTH and FGF23 levels." (PMID 30159331, 2018). "Collectively, this suggests a cardioprotective effect of Klotho in the setting of CKD that is independent of FGF23 excess, hyperphosphatemia and hypertension." (PMID 30200452, 2018). "One hypothetic explanation is that hyperphosphatemia is prevented until the later stages of CKD by parathyroid hormone (PTH) and fibroblast growth factor-23 (FGF-23), which in turn suppress renal phosphate reabsorption and augment renal phosphate excretion in these patients." (PMID 30301260, 2018). "Furthermore, 5/6-Nx mice showed hyperphosphatemia, increased total serum alkaline phosphatase (ALP) activity, severe secondary hyperparathyroidism, and elevated serum intact Fgf23 levels, relative to Sham controls." (PMID 29942284, 2018). "Hyperphosphatemia occurs when the homeostasis of phosphate is altered, as described in patients with CKD and in the premature aging syndromes presented in the Klotho mice and FGF23 KO mice." (PMID 28857396, 2017). "Significant hyperphosphataemia without a dose-dependent change in FGF23 has been observed with other selective FGFR inhibitors." (PMID 28972963, 2017). "In contrast to previous studies in normophosphatemic subjects, one study attempted to investigate whether sevelamer carbonate could lower FGF23 levels in patients with CKD (Stages 3–5) and hyperphosphatemia." (PMID 26221597, 2015). "Therefore, cleaning the FGF-23 of the MHD patients, and then reducing hyperphosphatemia due to elevated serum FGF-23 level, and ultimately resulting in improvement of the long-term prognosis of patients, are the important issues of blood purification." (PMID 24669256, 2014). "In a pivotal study of 100 CKD stage 4 patients with hyperphosphatemia (> 6.0 mg/dL), it was demonstrated that Sevelamer but not calcium acetate was able to reduce FGF23 and improve endothelial function." (PMID 25032144, 2014). "The lack of effect of HS219 on serum FGF23 levels provides additional evidence that HS219 does not affect phosphorus metabolism in HD patients with hyperphosphatemia." (PMID 24968790, 2014).
hyperphosphatemia (continued). "Therefore, the treatment of hyperphosphatemia clinically controls Pi levels, however, is also required to control the serum Ca, PTH and FGF-23 levels, as dietary Pi restriction and Pi removal via blood purification alone are insufficient." (PMID 24669256, 2014). "FGF23 may also bind FGFR4, FGFR1 IIIc and FGFR3 IIIc, but the relative contribution of individual FGFR subtypes to hyperphosphatemia remains unclear." (PMID 23900974, 2013). "Increased FGF23 concentration was not explained by its classical determinants: hyperphosphataemia, increased calcitriol concentration or decreased renal function." (PMID 23825530, 2013). "In general, patients did not have hyperphosphatemia but vitamin D levels were low and FGF-23 levels were elevated." (PMID 23351146, 2013). "The epididymal phenotype of Fgf23-/- mice does not appear to be mediated via systemic hyperphosphatemia as a high phosphate dietary exposure for weeks did not result in testicular or epididymal microcalcifications or changes in testicular phosphate transporter expression." (PMID 40279260, 2025). "Interestingly, loss-of-function variants in the GALNT3 gene (protein name: GalNAc-T3) and hence a lack of degradation-protective glycosylation of FGF23 leads to systemic hyperphosphatemia and severe testicular microcalcifications." (PMID 40279260, 2025). "Conversely, a lack of FGF23 induces hyperphosphataemia and high serum 25-OH-D3." (PMID 38396804, 2024). "Furthermore, genetic mouse models lacking klotho or FGF23 do not develop severe kidney damage but hyperphosphatemia as well as skeletal muscle wasting and atrophy." (PMID 38791164, 2024). "Furthermore, not only mice with genetic deletion of klotho but also of FGF23 with normal klotho levels develop hyperphosphatemia in the absence of severe kidney damage that is accompanied by skeletal muscle wasting and atrophy." (PMID 39273260, 2024). "Thus, as CKD progresses, there is a dysregulation of the FGF23–Klotho axis, meaning that increased FGF23 levels are no longer able to enhance the excretion of phosphorus, leading to hyperphosphatemia, which further stimulates FGF23 secretion from the bone." (PMID 39339698, 2024). "Our data show that intake of a phosphate-rich diet results in inflammation-induced hypoferremia and ineffective erythropoiesis leading to anemia through the actions of elevated FGF23 on erythroid progenitors, in the absence of hyperphosphatemia and despite increased EPO secretion." (PMID 39666728, 2024). "However, if Ca2+ levels are high but Vitamin D signaling is low, the defense mechanism against hyperphosphatemia is not triggered to its full potential, and the FGF23 levels do not increase as much." (PMID 35807756, 2022). "Whether or not hyperphosphatemia and/or reduced klotho levels are the major driver for the cardiac toxicity of high FGF23 in CKD has to be confirmed in further studies." (PMID 34778257, 2021). "Therefore, increased blood FGF‐23 concentrations plausibly can reflect phosphate accumulation in dogs with CKD but without overt hyperphosphatemia." (PMID 34418162, 2021). "Moreover, hyperphosphatemia in glial cells missing homolog 2 (Gcm2) null mice and the addition of phosphate to osteoblast cultures did not result in increased Fgf23 transcripts, a result that was also found in other studies." (PMID 33716961, 2021). "Similarly, the lack of effects of LCN2 on FGF23 in a model of diet-induced hyperphosphatemia suggests that LCN2 does not play a role in phosphate-induced FGF23 production." (PMID 34334787, 2021). "This may represent a mechanism to prevent hyperphosphatemia when the circulating levels of FGF23 are not adequate." (PMID 33716961, 2021). "Therefore this remaining proportion of iFGF23 could collectively reflect additional stimulators of FGF23 in CKD, such as hyperphosphatemia, inflammation, and PTH among others." (PMID 32476270, 2020).
hyperphosphatemia (continued). "In addition to the reduction in CrC, our data reproduced the kinetics of both early and late biochemical indicators of CKD MBD; early biochemical markers included a rise in FeP and FGF-23 levels, with elevation of PTH levels and hyperphosphatemia as late markers." (PMID 31419270, 2020). "Thus, to the authors’ current knowledge, the direct induction of VC results from hyperphosphatemia rather than elevated FGF23 levels in CKD patients." (PMID 31698866, 2019). "Finally the elevated FGF23 levels can no longer compensate for dietary phosphorus overload which contributes to overt hyperphosphatemia in advanced stages of CKD." (PMID 30159331, 2018). "Therefore, in the setting of impaired kidney function, the phosphaturic action of FGF23 is not able to correct the hyperphosphatemia in more advanced CKD." (PMID 29892265, 2018). "However, several studies in human CKD patients have shown that the early increase in circulating intact FGF23 occurs independent of hyperphosphatemia and increased PTH." (PMID 29942284, 2018). "Indeed, FGF-23-blocking antibody has not been shown to safely reduce FGF-23 in CKD without worsening hyperphosphatemia." (PMID 29946298, 2018). "Future studies should determine the impact of cardiac FGF23/FGFR4 signaling in comparison to other potential factors, such as hyperphosphatemia or hypertension, which based on the increased duration of impact might also have more damaging effects in slow-progressing Col4a3 knockout mice." (PMID 29770125, 2018). "This explanation, however, does not account for the hyperphosphatemia and compensatory increments in serum FGF-23 concentrations in mice with conditional deletion of α-Kl in the distal tubule, which appears to support the presence of a distal to proximal tubule feedback mechanism." (PMID 26839958, 2016). "The significance of Klotho and FGF23 partly lies in the possibility that their dysregulation represents the earliest alterations in CKD and diabetic nephropathy, prior to detectable changes in vitamin D and PTH and much earlier than the occurrence of hyperphosphatemia and hypocalcaemia." (PMID 27668003, 2016). "The pathophysiology of SRH is complex and involves phosphorus retention leading to hyperphosphatemia, ionized hypocalcemia, decreased circulating 1,25-dihydroxyvitamin D (calcitriol) concentration and increased concentrations of parathyroid hormone (PTH) and fibroblast growth factor 23 [FGF23,]." (PMID 25333360, 2014). "Due to the lacking suppressive effect of Fgf23 on renal 1α-hydroxylase activity, Kl−/− and Fgf23−/− mice produce excessive amounts of 1,25(OH)2D, and die early from the sequelae of hypervitaminosis D, hypercalcemia and hyperphosphatemia." (PMID 24434184, 2014). "Fibroblast growth factor 23 (FGF23) is a recently discovered 30 kDa bone-derived circulating hormone that plays an important role in the complex and tightly regulated mechanism of mineral metabolism, including hyperphosphatemia, vitamin D insufficiency, and elevated parathyroid hormone (PTH) levels." (PMID 24015259, 2013). "Burosumab is a recombinant human monoclonal antibody (IgG1) that binds to FGF23 and inhibits its activity, but to date, it is only indicated for XLH-linked hypophosphatemia; it is not indicated for CKD due to the risk of severe hyperphosphatemia that patients may experience." (PMID 41426862, 2025). "Thus reducing FGF23 in CKD to a level that does not induce hyperphosphatemia may provide critical ancillary benefit." (PMID 32476270, 2020). "Existing evidence suggest that although very high levels of FGF23 in a CKD scenario may be deleterious to the myocardium, implying in a maladaptation, at a “physiological” levels for a CKD scenario, FGF23 is fundamental for protecting the body from hyperphosphatemia-related cardiovascular injury." (PMID 30087898, 2018).
hyperphosphatemia (continued). "However, phosphaturic factors such as fibrobast growth factor 23 (FGF23) or parathyroid hormone (PTH) are significantly increased at earlier stage of CKD and may compensate for a positive phosphate balance and prevent from hyperphosphatemia." (PMID 25032144, 2014). "Serum FGF-23 levels have been reported to increase in the very early stages of CKD, and the increase may represent a long-term, delayed response to transient episodes of hyperphosphatemia occurring in the early stage of CKD, possibly when the rapid response of PTH is becoming insufficient." (PMID 21234310, 2010). "The health impact of an increase in FGF23 without CKD, hyperphosphatemia and elevated PTH is unclear." (PMID 38770543, 2024). "In the kidney, phosphate reabsorption depends on parathyroid hormone (PTH), fibroblast growth factor 23 (FGF23) and dietary phosphate, but in CKD patients, hyperphosphatemia is a complication independent of PTH and calcitriol levels." (PMID 35203651, 2022). "Lack of FGF23 or its regulatory proteins (ppGalNacT3 and alpha-klotho) in FTC results in hyperphosphatemia and calcinosis at various sites." (PMID 34199304, 2021). "Although SIK inhibition is not involved in PTH-mediated phosphaturia, indirectly, SIK inhibition might even correct hyperphosphatemia in hypoparathyroidism, which is a consequence of absent PTH and inappropriately low FGF23." (PMID 37115697, 2023). "In rats with 5/6 Nx, there was also no hyperphosphatemia, but secondary hyperparathyroidism and elevated FGF23 levels were observed compared with sham rats; however, treatment with PF-06869206 did not reduce PTH or FGF23 levels." (PMID 34994388, 2022). "In addition, lanthanum carbonate, in RCT of CKD stage 3b/4 patients without hyperphosphatemia, did not significantly affect on arterial stiffness, aortic calcification, and serum phosphorus, PTH, and FGF23 levels for 96 weeks." (PMID 34069053, 2021). "Despite the presence of phosphate retention in this early period, hyperphosphatemia does not develop until later stages owing to an increase in parathyroid hormone (PTH) and fibroblast growth factor 23 (FGF-23) whose actions result in augmented urinary phosphate excretion." (PMID 23324569, 2013). "Moreover, the rise in serum FGF23 occurred in the complete absence of hyperphosphatemia in 5/6-Nx mice on either ND or CPD, further corroborating the notion that the early increase in FGF23 in CKD patients occurs independent of hyperphosphatemia and elevated PTH6." (PMID 34290280, 2021). "Hyperphosphatemia is only seen in older, more slowly or non-growing Fgf23/VDR compound mutant mice beyond 3 months of age, suggesting that the phosphaturic effect of FGF23 is physiologically less essential compared with the 1α-hydroxylase-suppressing effect, at least in mice." (PMID 29892265, 2018).